IL1B (interleukin 1 beta)
Diseases named in the same sentence as IL1B in open-access papers (continued):
Sharing a sentence is not in itself a finding about the gene and the disease.
intestinal disease (19 papers, 2014 to 2025). "During piglet production, weanling stress may induce intestinal disorders with increased pro-inflammatory cytokine secretion such as IL-1β, IL-6, and TNF-α, which cause growth retardation." (PMID 35814707, 2022). "In the context of intestinal disorders, IL‐1β acts as a crucial mediator of innate immunity and inflammation, leading to tissue damage." (PMID 40129999, 2025). "Bacterial diarrhea is an intestinal disease mediated by the overproduction of proinflammatory cytokines, including IL-1β, TNF-α, etc.." (PMID 35696408, 2022). "It normally causes mucosal inflammation, intestinal ulcers, and histological damage and triggers colonic expression of the proinflammatory cytokines TNF-α, IL-1β, and IL-6 in 14 days after the TNBS administration." (PMID 25729217, 2015). "In this manuscript, we found that IL-1β and IL-6 levels increased in CD enterocytes, not only in the acute phase of the disease but also in the remission phase and in potential patients before the onset of intestinal disease." (PMID 35216089, 2022). "We show that caspase-11 is required for IL-1β- and LPS-driven STAT1 activation in IECs, suggesting that caspase-11 facilitates crosstalk between MyD88 and STAT1 signalling pathways at the intestinal barrier, to promote anti-tumorigenic signalling during inflammation-associated intestinal disease." (PMID 30538296, 2019). "These intestinal disorders are promoted by the release of pro-inflammatory cytokines (TNF-α, IL-1β, and IFN- γ) that inhibit the mRNA expression of TJ proteins." (PMID 38019021, 2024). "Pro-inflammatory cytokines, such as IL-1β, IL-6, and TNF-α, serve to stimulate inflammatory responses and promote the occurrence of intestinal diseases." (PMID 36359981, 2022). "Intestinal disease in the A1 birds appears to be a consequence of a poorly regulated immune response, as expression levels of proinflammatory signals such as CXCL chemokines and IL-1β remain higher than in the three other breeds at 5 and 12 dpi." (PMID 24987092, 2014). "This is in line with observations that dietary gangliosides can interrupt pro-inflammatory signalling via IL-1β in the intestinal mucosa, specifically suppressing production of IL-1β, NO, PGE2, hydrogen peroxide, IL-6 and IL-8, and subsequently alleviating symptoms of intestinal disease." (PMID 32679677, 2020). "However, CGRP, whose role in intestinal diseases has not been fully elucidated, may inhibit the expression of TNF-α and IL-1β and take part in mechanisms connected with the development of diarrhoea." (PMID 30154361, 2018).
liver (19 papers, 2009 to 2025). "Through the analysis of relative gene expression in the mouse colonic mucosa with qPCR, we confirmed aggravated colon inflammation through the increased expression of proinflammatory gene mRNA, such as Tnf-α and Il1β." (PMID 35662934, 2022). "A study by Weiet al. on 48 subjects who had undergone gastrointestinal tumor resection also found a significant reduction in mean IL-1β level on group receiving intravenous LCT/FO lipid emulsion compared to group receiving intravenous LCT lipid emulsion." (PMID 33299555, 2020). "Furthermore, an analysis of the effects of PCE on IL-6, IL-1β, and TNF-α expression in colonic epithelial cells of the rat colon carcinogenesis model showed an increase in IL-6, IL-1β, and TNF-α mRNA levels in the DMH + DSS group." (PMID 36900505, 2023). "Higher levels of TGF-β and lower levels of IL-1β, CD14, and CCR5, markers of circulating neutrophils, suggest that TOLLIP deficiency may facilitate the resolution of chronic inflammation during colon carcinogenesis." (PMID 36499030, 2022). "It is widely reported that cytokines (IL1β, TNF-α), matrix metalloproteinase (MMP-7, MMP-9) are involved in chronic inflammation, which creates a microenvironment favoring colon carcinogenesis." (PMID 23754197, 2013).
inflammatory myopathies (15 papers, 2012 to 2026). "Beyond IL-1β, recently studies suggest several cytokines and chemokines as important key molecules in the pathogenic mechanisms of inflammatory myopathies, such as IFNs and MCPs." (PMID 35965334, 2022). "Our data provides the first evidence that inhibiting IL-1β may improve muscle differentiation in dysferlin deficiency and thus presents a novel therapeutic avenue for treating inflammatory myopathies." (PMID 26251696, 2015). "Several key factors such as pro-inflammatory cytokines like TGF-β1 and IL-1β, drive fibrosis in WB myopathy." (PMID 41948366, 2026). "In this study, we define the specific transcriptomic features of GM, revealing a distinct activation of the IFNγ pathway compared to other myopathies, as well as an increase in multiple proinflammatory cytokines, including IL1B, TNF, and TGFB1." (PMID 40568658, 2025). "To corroborate these results, we analyzed several inflammatory cytokines like IL-8, TNF-α, IL-1β and IL-17A in the plasma of these inflammatory myopathy patients following IVIG therapy." (PMID 31974400, 2020). "Increased plasma IL-1β levels were also seen in these patients, suggesting that IL-1β may be a potential biomarker for these myopathies." (PMID 34199845, 2021). "Resistin expression in muscle tissue was significantly higher in patients with inflammatory myopathies compared to controls, and resistin induced the expression of interleukins (IL)-1β and IL-6 and monocyte chemoattractant protein (MCP)-1 in mononuclear cells but not in myocytes." (PMID 22577940, 2012). "However, aside from directly accessing the myocytes, this virus can induce myopathy, muscle weakness and atrophy indirectly by upregulating proinflammatory cytokines, such as interleukin 1 beta (IL-1β) and 6 (IL-6), C-reactive protein (CRP), and tumor necrosis factor (TNF)." (PMID 34248502, 2021). "IL-1β is also increased in muscle of patients with inflammatory myopathies, while levels of IFN-γ are not particularly elevated." (PMID 24204966, 2013).
central nervous system diseases (13 papers, 2015 to 2024). "Similarly, pro-inflammatory cytokine TNF-α is related to agitation severity in AD and IL-1β is implicated in contributing to disease severity in various central nervous system diseases including AD." (PMID 37679689, 2023). "IL-1β maintains the immune response in central nervous system diseases and activates microglia and astrocytes." (PMID 39595080, 2024). "IL-1β contributes to the regulation of various chronic and acute inflammatory responses in central nervous system diseases." (PMID 26858639, 2016). "The secretion and maturation of IL-1β is regulated by the inflammatory activation of NLRP3, which induces various forms of inflammatory response, thereby promoting the development of central nervous system diseases." (PMID 38127000, 2023). "It is involved in astrocyte activation, generation of pro-inflammatory factors IL-6, IL-1β, and TNF-α, and macrophage and T-cell infiltration, thus leading to secondary inflammatory injury in central nervous system diseases." (PMID 31681297, 2019).
brain diseases (11 papers, 2014 to 2023). "This then leads to the activation of pro-inflammatory cytokines interleukin (IL)-1β, IL-18, and IL-33, which promote a number of innate immune processes associated with infection, inflammation and autoimmunity, thereby responsible for neuroinflammation and associated brain diseases." (PMID 25339862, 2014). "The method of down-regulation of IL-1β by RNA interference during HI may protect against drain edema, stoke and other brain disorders via up-regulation of IL-6 expression." (PMID 24965599, 2015). "Induction of inflammasomes causes cleavage and release of IL-1β and IL-18, representing pathogenic processes that underlie inflammatory diseases although their contribution HIV-associated brain disease is unknown." (PMID 24886384, 2014). "Although in the CNS we may not observe all the manifestations of peripheral inflammation (i.e., no swelling), morphological changes in microglia, together with increased expression of IL-1β, is frequently observed in both human and animal models of brain diseases." (PMID 33363485, 2020). "In addition, studies have shown that moderate physical exercise could reduce the levels of IL-1β and TNF-α in the hippocampus or serum in interventions for brain disorders, although the effect on IL-6 is subject to specific discussion." (PMID 36212646, 2022).
hematological malignancies (11 papers, 2019 to 2025). "Variants impacting IL-1β are reported to influence risk of IA in patients with hematologic malignancies, and following solid organ transplant; the genes harboring risk variants include IL1A, IL1B, IL1RA, and IL1RN." (PMID 32185141, 2020). "Our data support that loss of repression of IL-1β through low IL-1RN may originate and worsen hematopoietic disease, and predicts poor survival in AML patients." (PMID 36596811, 2023). "IL-1B is a pleiotropic inflammatory cytokine whose over-expression is a common event in patients with hematological malignancies." (PMID 35371979, 2022). "Currently, multiple clinical trials are targeting the IL-1 family in hematological malignancies, examining predominantly the therapeutic values of either anakinra (antagonist of IL-1R) or canakinumab (IL-1β-neutralizing monoclonal antibody)." (PMID 35897704, 2022). "The functional role of IL-1β in hematological malignancies has been elucidated in recent studies and is summarized in several reviews." (PMID 33525345, 2021). "In preclinical models of hematological and non-hematological malignancies, the antitumoral effects of IL-1β have been investigated for decades." (PMID 33530653, 2021). "Clinical studies targeting IL-1β have already been performed in both solid tumors and hematological malignancies." (PMID 31139332, 2019). "IL-1rn-KO mice develop an IL-1β-induced phenotype reminiscent of early hematopoietic disease." (PMID 36596811, 2023).
neurodevelopmental disorder (9 papers, 2014 to 2026). A behavioral and cognitive disorder with onset during the developmental period that involves impaired or aberrant development of intellectual, motor, or social functions. "As a consequence, an increase in pro-inflammatory cytokines (e.g., IL-1B, IL-6, IL-8, and IL-12p40) was observed, which are associated with impaired social communication and neurodevelopmental disorders." (PMID 31752095, 2019). "It is considered that inflammatory processes stimulated by IL-1β are associated with an increased risk of neurodevelopmental disorders." (PMID 29973222, 2018). "Elevated levels of IL-1β in the circulation shortly after preterm birth are also associated with increased risk of neurodevelopmental disorders." (PMID 24950657, 2014). "This evidence indicates that dysfunction of IL-1β signaling might be involved in the pathogenesis of some neurodevelopmental disorders." (PMID 24950657, 2014). "Thus, it is important to elucidate whether IL-1β mediates neuronal differentiation to understand neural development and the pathogenesis of various neurodevelopmental disorders." (PMID 29973222, 2018). "Thus, studies of whether IL-1β regulates neuronal migration are important to further our understanding of brain development and the pathogenesis of some neurodevelopmental disorders." (PMID 24950657, 2014). "Elevated levels of inflammatory cytokines such as IL-6, IL-1β, and TNF-α in blood and cerebrospinal fluid have been reported in patients with neurodevelopmental disorders." (PMID 41465426, 2025). "The selected cytokines comprised IL-1β, IL-6, IL-10, TNF-α, and IFN-γ, which have not only been found dysregulated in the MIA paradigm, but also form part of the inflammatory profiles in the neurodevelopmental disorders reflected in the MIA model (eg)." (PMID 39033141, 2024). "In this way, the dysregulation of IL-1β and IL-6 (altered in ASD and ADHD adolescents in this study) could represent potential biomarkers of both neurodevelopmental disorders, ASD and ADHD." (PMID 37511467, 2023).
vasculopathy (8 papers, 2022 to 2025). "Other pro-inflammatory cytokines, such as interleukin-1β (IL-1β), were also found to contribute to KD vasculopathy, so further studies are warranted to explore the role of platelet-derived miR-223 in IL-1β induced vasculopathy." (PMID 35983051, 2022). "The cause of central nervous system inflammation and vasculopathy caused by NB may be the invasion of the central nervous system by Brucella, which interacts with astrocytes and microglia and induces the secretion of TNF-α, IL-1β and IL-6 by astrocytes and microglia." (PMID 38730327, 2024). "N153S animals have also been shown to overexpress IL-1β, IL-6, and MIP-1α in their lungs as an attribute of the vasculopathy they experience." (PMID 35769461, 2022). "Collectively, our findings suggest Ap4 as a novel pro-inflammatory mediator capable of inducing IL-1β release in innate immune cells through distinct mechanisms from classical NLRP3 inflammasome activators, shedding light on its potential role in inflammatory diseases and vascular disorders." (PMID 39984847, 2025).
musculoskeletal diseases (6 papers, 2013 to 2025). "Specifically, EA can modulate the release of pro-inflammatory cytokines such as IL-6, TNF-α, and IL-1β, which are key mediators of the inflammatory response in musculoskeletal disorders." (PMID 41567770, 2025). "For example, serum levels of TNF-α, IL-1β and IL-6 correlate positively with presence of musculoskeletal disorders symptoms in patients, and TNF-α levels are even predictive of symptom severity." (PMID 24015193, 2013). "RCTs and clinical trials revealed, after BT, a reduction in circulating levels of pro-inflammatory molecules, such as TNF-α, IL-1β, and C-reactive protein, and an increase in anti-inflammatory molecules such as the IGF-1 growth factor especially in musculoskeletal diseases." (PMID 34035862, 2021).
gastrointestinal disease (5 papers, 2018 to 2025). A disease that occurs in the gastrointestinal system, excluding the hepatobiliary system. "Modulation of downstream inflammasome mediators (like IL-1β and IL-8) may be a promising intervention for gastrointestinal diseases." (PMID 40444007, 2025). "Recent studies using rat models of gastrointestinal disease have found that taVNS upregulates intestinal ACh and α7nAChR expression, while simultaneously reducing the levels of inflammatory cytokines such as TNF-α, IL-1β, and IL-6." (PMID 40564012, 2025).
movement disorder (5 papers, 2021 to 2025). Neurological conditions resulting in abnormal voluntary or involuntary movement, which may impact the speed, fluency, quality and ease of movement. "ACR caused movement disorders, triggered oxidative stress, and raised TNF-α, IL-1β, and caspase-3 cleaved levels." (PMID 38333747, 2024). "In summary, there appears to be an increase in proinflammatory cytokines most clearly for TNF-α, but probably also for IL-17 and IL-1β, in children with obsessive-compulsive and movement disorder symptoms compared to healthy controls." (PMID 36061386, 2022). "Compared to the ACR-treated rats, administration of vitamin E reduced movement disorders, decreased MDA levels, increased GSH content, and lowered levels of TNF-α, IL-1β, and cleaved caspase-3 in rat cortical tissue." (PMID 40292259, 2025). "The present results indicate that the injection of ACR (50 mg/kg) for 11 days significantly led to movement disorders, decreased GSH content, and increased amounts of MDA, TNF-α, IL-1β, and caspase-3, resulting in the induction of oxidative stress, inflammation, and apoptosis in the brain cortex." (PMID 38333747, 2024).
gastrointestinal disorders (4 papers, 2018 to 2024). "Additionally, we introduce novel biologics and antagonists, such as inhibitors of IL-1β and inflammasomes, as therapeutic strategies for treating gastrointestinal disorders when inflammasomes are dysregulated or the composition of gut microbiota changes." (PMID 38566180, 2024).
gynecological diseases (3 papers, 2014 to 2021). "Clearly, the potential for confounding clinical parameters to influence the impact of urinary IL-1β levels for gynecologic disease warrants further investigation." (PMID 25403235, 2014). "Further, urinary levels of IL-1β levels/BMI as a prognostic indicator of gynecologic disease could impact clinical practice." (PMID 25403235, 2014). "Consequently, urinary IL-1β levels/BMI may prove to be useful prognostic indicator of gynecologic disease." (PMID 25403235, 2014).
head and neck tumors (3 papers, 2021 to 2025). "In addition, microarray analysis (GSE13597, GSE53819, and TCGA) revealed that AK4 expression was positively correlated to IL-1β expression in NPC and head and neck tumor samples." (PMID 40593461, 2025). "In this study, it was found that IL-1α, IL-1β, IL1R1, IL1RL1, IL1F10, IL33, CASP1, and AIM2 were highly expressed in head and neck tumors, while IL1RN, IL1RAPL1, IL1RAPL2, IL18BP, IL18R1, and IL18RAP were low in expressed, which is consistent with previous literature." (PMID 39461030, 2024).
genetic diseases (2 papers, 2012 to 2023). "The demonstration here that loss of pyrin can result in increase in IL-1β release is consistent with the original designation of FMF as a recessive genetic disorder." (PMID 23226472, 2012).
hematologic cancer (1 paper, 2022). "We also observed increased concentrations of CCL2, CCL3, CCL4, VEGFA and IL-1β in Severe-Death hematologic cancer patients." (PMID 36700209, 2022). "Within the hematologic cancer patient cohort there was a striking increase in the levels of the chemokines CCL2, CCL3, CCL4, CXCL8, and the cytokine IL-1β, in the Severe-Death group compared to the Mild group." (PMID 36700209, 2022).
osteoarthropathy (1 paper, 2010). "This fact suggests that osteoarthropathy in CINCA/NOMID is caused by overproduction of IL-1β, as are the symptoms of autoinflammation and disappearance of them by specific receptor antagonist of IL-1β." (PMID 20230645, 2010).
IL1B also shares sentences with these, for which no sentence is quoted: acute myocardial infarction (47 papers); multiple myeloma (23); idiopathic pulmonary fibrosis (19); cardiac arrhythmias (12); chronic prostatitis (9); essential hypertension (9); acute cystitis (8); corneal ulcer (7); colon (6); viral diseases (6); acute myocarditis (5); magnesium deficiency (5); neuromyelitis optica (5); acute respiratory failure (4); chronic hepatitis (4); Disseminated intravascular coagulation (4); ductal carcinoma in situ (4); falciparum malaria (4); hyperparathyroidism (4); hypertrophy (4); Myalgia (4); pelvic inflammatory disease (4); pemphigus vulgaris (4); polymyositis (4); Sleep disturbance (4); tonsillitis (4); Acute otitis media (3); childhood asthma (3); clear cell renal carcinoma (3); end-stage renal disease (3).
A further 380 diseases each share a sentence with IL1B in 3 papers or fewer.